BRCA1 (BRCA1 DNA repair associated)
Diseases named in the same sentence as BRCA1 in open-access papers (continued):
Sharing a sentence is not in itself a finding about the gene and the disease.
breast cancer (continued). "As an additional control group, we also performed IGF1 genotyping on 86 women with available DNA from the South Swedish BRCA1 mutation families who did not carry the mutation in their respective families and who did not have breast cancer at the time of testing." (PMID 15756256, 2005). "Finally, in the context of genetic counselling, specific tumour characteristics may help evaluate the possibility of a BRCA1 or BRCA2 mutation and the need for mutation testing in a family with a history of breast cancer." (PMID 15987451, 2005). "Germline mutations in the BRCA1 (MIM#113705) and BRCA2 (MIM#600185) genes account for genetic predisposition and increased risk for breast and ovarian cancer in the majority of families with inherited predisposition to both these neoplasms and in 20–40% of families with site-specific breast cancer." (PMID 15756275, 2005). "However, the majority of individuals referred to cancer genetic services due to a family history placing them at increased risk of developing breast cancer do not have BRCA1/2 mutations." (PMID 15138471, 2004). "Multiple studies have found an elevated frequency of the 1100delC variant in specific stratifications of breast cancer patients with a family history of the disease, including BRCA1/BRCA2 negative families and families with a history of bilateral disease or male breast cancer." (PMID 15535844, 2004). "Thus far, the most convincing evidence for an association between the 1100delC variant and breast cancer risk is in families who do not carry BRCA1/BRCA2 germline mutations." (PMID 15535844, 2004). "The number of women in the present study with a first-degree family history of breast cancer who tested negative for BRCA1/BRCA2 mutations (71 cases, 27 controls) does not offer adequate power to detect differences in the frequency of CHEK2 variants within this stratification." (PMID 15535844, 2004). "To investigate if variants of CHEK2 other than 1100delC confer an increased risk of breast cancer, we have screened a series of 68 familial breast cancer cases, which had been screened in the Regional Genetics Service and found to be negative for mutations in BRCA1 and BRCA2." (PMID 12454775, 2002). "Some of this excess risk of prostate cancer may be due to mutations in BRCA1 and BRCA2." (PMID 11875732, 2002). "In the context of high-risk families the most important genes are BRCA1 on chromosome 17q, which is associated with a high penetrance of both breast and ovarian cancer, and BRCA2 on chromosome 13q, which causes a high risk of breast cancer but a lower risk of ovarian cancer." (PMID 7547224, 1995). "Furthermore, ELF3 knockdown in HCC1937 and SUM149PT cells, both of which are human breast cancer cell lines with BRCA1 mutations and allelic loss, also caused a significant decline in cell proliferation, suggesting that ELF3 is essential for BRCA1 mutant breast cancer cell survival." (PMID 41498327, 2026). "It was previously reported in a Spanish family with non-BRCA1/BRCA2 early breast/ovarian cancer family history and the incidence of pancreatic cancer, as well as in a patient with unilateral breast cancer from the WECARE study." (PMID 40040726, 2025). "The correlation analysis of HA, CD44, BRCA1, and BRCA2 showed only one strong correlation, BRCA1 and BRCA2 in breast cancer (r = 0.7; p < 0.0001), while in the case of colorectal cancer this correlation was much weaker (r = 0.5; p = 0.02)." (PMID 41373491, 2025). "We found a correlation in breast cancer between CD44 and BRCA1, although it was a weak correlation with strong statistical significance." (PMID 41373491, 2025). "For instance, B3GNT7 and CTSV predicted detrimental prognosis in BRCA2-mut breast cancers, and CD6, CXCL9, and CXCL13 predicted favorable outcomes in BRCA1-mut ovarian cancers." (PMID 40647506, 2025). "In striking contrast to the BRCA1/2-proficient SKBR3, MDA-MB231, and JIMT1 breast cancer cells, the dual inhibition of CASP3 + 7 was lethal in SUM149PT cells." (PMID 39982959, 2025).
breast cancer (continued). "There was also a correlation between PARP2 and BRCA1/2 and ESR1 in the HER2 subgroup of breast cancer patients." (PMID 40141415, 2025). "An estimated 40% (95% CI, 35%–45%) of BRCA1 carriers and 26% (95% CI, 20%–33%) of BRCA2 carriers develop contralateral breast cancer within 20 years following an initial breast cancer diagnosis." (PMID 41083355, 2025). "Since its overexpression has been described in BRCA1-deficient mouse mammary tumors, researchers investigated whether EZH2 was essential for cancer cell survival or a tumorigenic byproduct, demonstrating an EZH2-dependence, while BRCA1-intact cells tolerate EZH2 loss." (PMID 40136510, 2025). "In this study, the ability of RAPTA-T and olaparib in combination and as single agents to inhibit triple-negative BRCA1 wild-type MDA-MB-231 and MDA-MB-468 cells compared with sporadic BRCA1 wild-type MCF-7 breast cancer cells was investigated." (PMID 41226649, 2025). "The reported family history for the identified BRCA1, BRCA2 and PALB2 carriers revealed additional breast cancer diagnoses in 1st or 2nd degree relatives for over half of the cases, whereas ovarian cancers were less frequent." (PMID 40009290, 2025). "Tamoxifen-resistant breast cancer cells exhibit significantly elevated levels of BARD1 and BRCA1, contributing to their resistance to DNA-damaging chemotherapy." (PMID 39858015, 2025). "Particular attention is given to the different clinical behaviors of breast cancer according to the specific BRCA gene, thus differentiating between BRCA1 and BRCA2 carriers." (PMID 40979227, 2025). "For breast cancer, there were 6 genes with a posterior probability > 0.9: BRCA2, BRCA1, PALB2, CHEK2, ATM, and MAP3K1." (PMID 40073867, 2025). "BRCA1 CNV detection in whole blood-derived ovarian and breast cancer sample achieved 100% concordance with MLPA, supporting that ddPCR’s comparability with the established gold standard method for CNV assessment." (PMID 40725150, 2025). "PARP inhibitors in BRCA1/2 positive cases can improve progression‐free survival (PFS) and overall survival (OS) in breast cancer, ovarian cancer and pancreatic cancer." (PMID 40747594, 2025). "Among HER2 + stage I-III breast cancers with early (N = 20) and late (N = 20) recurrence, the most frequent alteration, other than HER2 amplification, was PIK3CA (45% vs 25%), followed by BRCA1/2 (10% vs 5%), ESR1 (0% vs 5%), PD-L1 amplification (5% vs 0%)." (PMID 40421962, 2025). "Of the 307 patients with breast cancer, 33% had VUS, primarily in ATM (12%), BRCA2 (11%) and BRCA1 (5%)." (PMID 40259910, 2025). "As these differences were exclusively observed in the group with no personal history of breast cancer, we hypothesized these results may be due to the lack of perception of the true risk of developing breast cancer in carriers of P/LP variants in BRCA1/2 genes." (PMID 40445415, 2025). "Other interesting observations included the mutual exclusivity of KEAP1 and STK11 in NSCLC and enrichment for CDH1, PIK3CA, and ARID1A along with mutual exclusivity with BRCA1/2, PTEN, and ESR1 in breast cancer." (PMID 40178042, 2025). "As a nuclear transport protein, KPNA2 is involved in the cytoplasmic retention of key DNA damage response proteins including BRCA1, RAD51, and CHK1 in breast cancer cells." (PMID 40002266, 2025). "The findings from this study have highlighted the contribution of genetics, specifically BRCA1 and BRCA2 genes in 120 unselected series of Brunei breast cancer population." (PMID 40531958, 2025). "Pathogenic variants (PVs) in BRCA1 and BRCA2 are causative of hereditary breast and ovarian cancer (HBOC), a hereditary syndrome associated with increased lifetime risk of breast cancer (BC) and ovarian cancer (OC)." (PMID 40649708, 2025). "After exclusion of 3 (1.0%) patients with stage IV disease, the final analytic cohort included 309 BRCA1/2 and PALB2-positive women with operable breast cancer; 160 (51.8%) BRCA1, 130 (42.1%) BRCA2, and 19 (6.1%) PALB2 carriers." (PMID 40275390, 2025).
breast cancer (continued). "However, emerging evidence indicates that triple-negative breast cancer (TNBC) patients carrying pathogenic BRCA1 variants may experience significantly improved breast cancer-specific survival." (PMID 40870889, 2025). "Western blot employed to determine the expression of endogenous HCN2, HCN3, BRCA1, BRCA2, and RAD51, confirmed that either HCN2 or HCN3 was overexpressed in the breast cancer cells, whilst HEK293 had low expression in both of HCN2 and HCN3." (PMID 40764992, 2025). "For example, except for retinoblastoma, MutL Homolog 1 (MLH1) is frequently silenced in colorectal and endometrial cancers, while methylation of BRCA1 and RAD51C is commonly detected in ovarian and breast cancers." (PMID 41150792, 2025). "In BRCA1-mut breast cancer, KANK4, MFGE8, LINC00346, and A100A1 were upregulated (more than 3-fold change), and in BRCA2-mut breast cancers, MAGEA4 was highly expressed (more than 4-fold change)." (PMID 40647506, 2025). "BRCA1 and BRCA2 genes are the most well-known and well described predictors of hereditary breast cancer due to their clinical importance." (PMID 40531958, 2025). "The BRCA1 and BRCA2 genes, which stand for breast cancer gene 1 and gene 2, produce proteins that aid in the repair of damaged DNA in normal conditions." (PMID 40141415, 2025). "qPCR analysis confirmed the upregulation of BRCA1, cGAS, STING, SEI1, and PD‐L1 expressions in the breast cancer cell lines or lymphoma cell lines treated with melphalan or bortezomib." (PMID 40135791, 2025). "Beyond lowering breast cancer incidence, BRRM has also been shown to improve overall survival in BRCA1 carriers." (PMID 40974500, 2025). "In breast cancer, PP1 has been shown to interact with factors such as BRCA1 and DARPP-32, thereby playing a critical role in the tumor microenvironment and regulating processes such as cell migration." (PMID 40626009, 2025). "The most interesting finding of the MetaCore analysis was the significant correlation between GNPDA1 and BRCA1 and BRCA2 in breast cancer cells." (PMID 40278313, 2025). "Furthermore, if a mutation is found (i.e. in BRCA1/2 or CHEK2) then specific surveillance protocols may be recommended for the mutation carriers (usually for breast and other cancers, because most breast cancer susceptibility genes are associated with a multi-site cancer predisposition)." (PMID 40770660, 2025). "This study aimed to investigate the uptake of BRCA1/2 genetic testing and evaluate the awareness of and attitudes toward PGT‐M among patients with breast cancer who have undergone fertility preservation." (PMID 40969453, 2025). "With advancements in genomic profiling, for instance, the BRCA1/2, HER2, and PIK3CA genes, usually evaluated in breast cancer patients, are now easy to identify." (PMID 39852145, 2025). "Another weak correlation was found in the case of breast cancer, between CD44 and BRCA1 (r = 0.5; p = 0.02)." (PMID 41373491, 2025). "In the PPI network of 308 genes, several hub genes (ESR1, BRCA1, CREBBP, ERBB2, and LCK) are known to play critical roles in breast cancer development." (PMID 39888956, 2025). "This review examines the biological, clinical, therapeutic, and survivorship implications of breast cancer in young BRCA carriers, emphasizing differences between carriers of PVs in the BRCA1 and BRCA2 genes." (PMID 40979227, 2025). "First, GNPDA1 was strongly associated with “DNA damage_ATM activation by DNA damage (p = 4.282 × 10−06)”, “BRCA1 and BRCA2 in breast cancer (p = 6.950 × 10−04)”, and “DNA damage_ATM/ATR regulation of G2/M checkpoint: nuclear signaling (p = 8.093 × 10−04)”." (PMID 40278313, 2025).
breast cancer (continued). "Alterations in high-penetrance genes like BRCA1 and BRCA2 explain a proportion of familial breast cancers; however, they leave most sporadic cases unexplained." (PMID 41301862, 2025). "Third, key FA genes, including BRCA1 (FANCS) and BRCA2 (FANCD1), are well-established drivers of breast cancer." (PMID 40805278, 2025). "Stratifying the MWS analysis by age at diagnosis of breast cancer, we observed that among carriers of BRCA1 and BRCA2 PTVs, the odds ratio (OR) for breast cancer aged <55 (vs controls) was more than double that of breast cancer aged ≥55." (PMID 41044259, 2025). "This study presents a multi-omics analysis of acquired Olaparib resistance in BRCA1- and BRCA2-mutant breast cancer cell lines." (PMID 40669753, 2025). "From an oncological perspective, as BRCA1/2 protein defects sensitize breast tumor cells to various chemotherapeutic agents that induce DNA lesions, we investigated whether there was an association between tumor response to NAC and changes in AMH concentrations during NAC in breast cancer patients." (PMID 40220108, 2025). "This systematic review aims to broaden the discussion of BRCA1 and BRCA2 beyond mammary tumors, exploring their implications in various canine cancers." (PMID 40004231, 2025). "GNPDA1 and SLC25A16 play important roles in the BRCA1, BRCA2, and pro-oncogenic actions of the androgen receptor in breast cancer development." (PMID 40278313, 2025). "For our study, we selected group of 100 breast cancer patients who had previously been analyzed by MS-HRM and showed BRCA1 promoter methylation in peripheral blood and paired tumor tissue DNA." (PMID 40495194, 2025). "The variant was uncovered during routine germline genetic testing in a breast cancer patient and genotyped as a complete processed RPL18A transcript inserted into the coding region of the BRCA1 gene." (PMID 41375073, 2025). "For instance, in South Africa, genetic testing for the BRCA1 and BRCA2 genes in breast cancer has been implemented at the primary healthcare level for over two decades, with plans to upscale to a multigene next-generation sequencing (NGS) panel." (PMID 40313245, 2025). "BAP1 was first identified and isolated from breast cancer and lung cancer cell lines in 1998, named for its binding to the RING domain of the BRCA1 protein." (PMID 40918144, 2025). "At the pilot sites, PV/LPVs in breast cancer genes were most commonly identified in ATM, BRCA2, and BRCA1, whereas at the non-pilot sites, they were most commonly identified in BRCA2, BRCA1, and PALB2." (PMID 39292401, 2025). "Because of the higher prevalence of BRCA2 and other pathogenic germline variants, routine referral for genetic counseling and testing (including BRCA1, BRCA2, PALB2, and others as appropriate) is strongly recommended for all men diagnosed with breast cancer." (PMID 41510417, 2025). "The bioinformatics study revealed a correlation between PARP2 and BRCA1/2 and ERBB2 in the basal subgroup of breast cancer patients." (PMID 40141415, 2025). "Using this strict approach, we selected two genes associated with a detrimental prognosis: B3GNT7 and CTSV in BRCA2-mut breast cancers, and three with a favorable prognosis: CD6, CXCL9, and CXCL13 in BRCA1-mut ovarian cancers." (PMID 40647506, 2025). "Therefore, BRCA1-dysfunctional breast cancer may be particularly sensitive to certain classes of DNA-damaging drugs, such as platinum-based drugs as well as their derivatives, and relatively resistant to mitotic spindle poisons, such as taxanes and vinca alkaloids." (PMID 41155174, 2025). "We discovered the involvement of MBD protein in the control of BRCA1, BRCA2, and p16, as well as their impacts on breast cancer cells, in this work." (PMID 38711004, 2024). "We found that the treatment of Gata3+/− (p18−/−;Gata3+/−) mouse mammary tumor cells with VP16 led to significantly more γH2AX than the treatment of Gata3+/+;Brca1+/+ (MMTV-PyMT) tumor cells." (PMID 38627785, 2024).
breast cancer (continued). "For breast cancer, BRCA1 and BRCA2 OR values are approximately 11.6 and 8.9 respectively, while for ovarian cancer, BRCA1 and BRCA2 OR values are approximately 58.4 and 13.4 respectively." (PMID 39226245, 2024). "The second study evaluated the presence of BRCA1 and BRCA2 gene alterations in cats with mammary cancer as the feline tumours resemble basal-like triple-negative breast cancer in humans, which is associated with mutations in these genes." (PMID 38787171, 2024). "Our study aimed to assess BZA’s effects on Estrogen Receptor Alpha (ERα) and tumor suppressor gene BRCA1 in T-47D and MCF-7 breast cancer cells, using Western blots, cellular viability, apoptosis assays, and RT-qPCR." (PMID 38398090, 2024). "Conventionally, BRCA1/2 genes, which are part of the HRR pathway, have been utilized for testing in breast cancer patients." (PMID 38397152, 2024). "It has also been shown that 62% of breast cancers overexpress AURKA, which is responsible for blocking the function of BRCA1 during G2, the phase of the cell cycle when its activity is crucial for regulating the centrosome." (PMID 38606093, 2024). "While BRCA1 and BRCA2 expression levels of breast cancer stem cells to which we applied the same dose increased in terms of DNA DSB repair, in the current study, it was observed that BRCA1 and BRCA2 levels decreased, but there was no significant change." (PMID 38367174, 2024). "EMSA was performed to check the DNA binding activity of MBD proteins on BRCA1, BRCA2, and p16 gene promoter in breast cancer." (PMID 38711004, 2024). "However, conservative surgery is limitedly recommended to patients because it could be contraindicated, especially in young women with specific risk factors such as breast cancer with DCIS, tumors with lobular histology, a family history of genetic disorders, and carrying BRCA1/2 mutations." (PMID 39765590, 2024). "For example, BRCA1 negatively regulates autophagic vacuole formation in MCF-7 breast cancer cells, and downregulation of BRCA1 promotes breast cancer growth via the upregulation of autophagy." (PMID 38225560, 2024). "BRCA1 compound heterozygous mutations in exon 11 (c.4065-4068del–p.Asn1355Lysfs*10) and in intron 22 (c.5406 + 7A > G–p.Asp1778Glyfs*27) were reported in another patient, mother of a girl, that developed ovarian and breast cancers at 43 and 44 years, without any FA-like symptoms." (PMID 39596525, 2024). "The Talazoparib Beyond BRCA phase 2 study demonstrated the efficacy of Talazoparib, a PARPi, in advanced breast cancer with germline PALB2 PV/LPV, showing activity within the context of HRD beyond BRCA1/2." (PMID 39796639, 2024). "The best known are BRCA1 and BRCA2 which convey average lifetime breast cancer risks of 50% to 70% and significant risks for ovarian cancer and other malignancies." (PMID 39107016, 2024). "In the breast cancer cell line MCF-7, ATRA signaling requires BRCA1 and PALB2 for the modulation of all the retinoid regulated transcriptome including the classical retinoid-responsive HOXs (Homeobox genes) genes." (PMID 38360674, 2024). "Nevertheless, RRSO is associated with a significant reduction in PBC risk in BRCA2 carriers alone and improved breast cancer survival in BRCA1 and BRCA2 carriers previously diagnosed with breast cancer." (PMID 38256099, 2024).